RENO1 (regulator of early neurogenesis 1)
Gene: Long non-coding RNA gene on chromosome 17 (81,339,178 to 81,345,995, reverse strand). Ensembl gene ENSG00000287431.
Diseases named in the same sentence as RENO1 in open-access papers:
RENO1 is named in the same sentence as 3 diseases in open-access papers, as found by Europe PMC text mining. Sharing a sentence is not in itself a finding about the gene and the disease. The quoted sentences say what the papers report.
lung fibrosis (1 paper, 2023). "Notably, intratracheal administration of rENO1 induced lung fibrosis in mice and treating human lung tissue cores with rENO1 also significantly increased expression of various fibrosis proteins." (PMID 37964270, 2023).
infection (1 paper, 2015). The state of being infected such as from the introduction of a foreign agent such as serum, vaccine, antigenic substance or organism. "On the 6th day post infection, antibodies against rEno1, rPgk1, and rBgl2 can be detected in the mice sera and the antibody titers increasing gradually over time." (PMID 26441862, 2015). "Antibody titers to rEno1, rPgk1, and rBgl2 reached their peak on the day of 20, 24, and 16 post infection and then slightly dropped down." (PMID 26441862, 2015). "We also report the serodiagnosis of infection by invasive Candida species using ELISA to detect specific antibodies against rEno1, rPgk1, and rBgl2." (PMID 26441862, 2015).
RENO1 also shares sentences with these, for which no sentence is quoted: system candidiasis (2 papers).